TFEB (transcription factor EB)
Diseases named in the same sentence as TFEB in open-access papers (continued):
Sharing a sentence is not in itself a finding about the gene and the disease.
renal cell carcinoma (continued). "Of note, it has been demonstrated that renal cell carcinomas showing TFEB amplification harbor concurrent vascular endothelial growth factor A (VEGFA) gene amplification." (PMID 31382581, 2019). "It has long been documented that multiple translocation events, resulting in five described TFE3 gene-fusion products and one TFEB gene fusion product, result in renal cell carcinoma (RCC)." (PMID 30520728, 2018). "Translocations of the genes encoding the related transcription factors TFE3 and TFEB are almost exclusively associated with a rare juvenile subset of renal cell carcinoma and lead to over-expression of TFE3 or TFEB protein sequences." (PMID 17705868, 2007). "Interestingly, the translocation renal cell carcinoma (TRCC) driver gene TFEB is specifically activated in progenitor cells and shows an age-dependent decrease in activity." (PMID 38724668, 2025). "These drugs are effective for metastatic TFEB-translocated renal cell carcinoma." (PMID 38730456, 2024). "In this view, it is indeed worth mentioning that SFPQ/PFS::TFE3-rearranged renal cell carcinoma may morphologically mimic TFEB-rearranged renal cell carcinoma." (PMID 39410016, 2024). "Additionally, melanogenesis markers such as Melan-A and HMB45 are found in TFE3-rearranged renal cell carcinoma, although less frequently compared to their occurrence in TFEB-rearranged renal cell carcinoma." (PMID 39410016, 2024). "Interestingly, 1–5% of adult, and up to 40% of paediatric, renal cell carcinomas (tRCCs) are caused by chromosomal translocation of MiT/TFE family members, including TFEB." (PMID 37728021, 2023). "Additionally, in a renal-cell carcinoma model, the upregulation of PD-L1 was mediated by the translocation of transcription factor EB (TFEB) induced by the inhibition of mTOR." (PMID 37834467, 2023). "In addition to histomorphology, the immunophenotype of renal epithelioid-AML overlaps with MiT family renal cell carcinoma with TFE3 or TFEB translocation." (PMID 36740682, 2023). "Furthermore, S100A1 was typically positive and CK7 was usually negative regardless of the cutoff used either considering the overall MiT family translocation renal cell carcinomas or TFE3 and TFEB-rearranged renal cell carcinoma separately." (PMID 35980471, 2022). "Expression of CK7 and parvalbumin along with the absence of S100A1 is characteristic of chromophobe renal cell carcinoma, whereas strong and diffuse labeling of S100A1 along with the under-expression of CK7 and parvalbumin are typical of TFE3/TFEB-rearranged renal cell carcinoma." (PMID 35980471, 2022). "In conclusion, since TFE3/TFEB-rearranged renal cell carcinoma may mimic several histotypes, an immunohistochemical panel to differentiate them from common renal cell tumors should include cathepsin K, CA9, CK7, and parvalbumin." (PMID 35980471, 2022). "While the expression is lower for TFE3-rearranged renal cell carcinomas (41%, 33%, and 29% respectively with a 5%, a 10%, and 20% threshold), most of TFEB-rearranged renal cell carcinomas labeled positive for CK8-18 (100%, 80%, and 60% respectively with 5%, 10%, and 20% threshold)." (PMID 35980471, 2022). "These tumors may show overlapping morphological and immunohistochemical features with MiT family translocation renal cell carcinoma, especially with TFEB-rearranged renal cell carcinoma, both positive for cathepsin K and Melan-A." (PMID 35980471, 2022). "Moreover, in TFEB-rearranged renal cell carcinoma, cathepsin K and melanogenesis markers are constantly positive, whereas TFE3-rearranged renal cell carcinoma stains for cathepsin K in roughly half of the cases, HMB45 in 8% and Melan-A in 22%." (PMID 35980471, 2022). "The forthcoming Word Health Organization (WHO) includes TFE3-rearranged renal cell carcinoma and TFEB-rearranged renal cell carcinoma as separate entities differentiating from the previous one in which the term “MiT family translocation renal cell carcinoma” encompassed both tumor types." (PMID 35980471, 2022).
renal cell carcinoma (continued). "Finally, the study highlighted the importance, also from an immunohistochemical point of view, to maintain TFE3 and TFEB-rearranged renal cell carcinoma as distinct entities, as recommended by the forthcoming WHO classification of renal tumors." (PMID 35980471, 2022). "Recently, the expression of TRIM63 by RNA in situ hybridization (RNA-ISH) assay has been proposed as another diagnostic marker for TFE3 and TFEB-rearranged renal cell carcinoma even if an external validation has not been performed so far." (PMID 35980471, 2022). "Moreover, 7 of 10 (70%) and 2 of 10 (20%) TFEB-rearranged renal cell carcinomas revealed positive parvalbumin expression respectively considering a 5% threshold and both a 10% and a 20% threshold." (PMID 35980471, 2022). "For instance, staining for CD10 which is usually observed in TFE3-rearranged renal cell carcinoma and under-expressed in TFEB-rearranged renal cell carcinoma seems significant in the differential diagnosis of MiT family translocation renal cell carcinoma and clear cell renal cell carcinoma." (PMID 35980471, 2022). "About TFE3-rearranged renal cell carcinomas, immunolabeling was observed in roughly half of the cases (54% and 50% using the threshold of 5% and 10% or 20% positive cells respectively) whereas all the eleven TFEB-rearranged renal cell carcinomas evaluated stained positive for cathepsin K." (PMID 35980471, 2022). "TFEB or TFE3 fusion with other partner genes may be the initiating factors for MITF translocation renal cell carcinoma." (PMID 36550835, 2022). "We performed an immunohistochemical panel comparing 27 TFE3-rearranged and 10 TFEB-rearranged renal cell carcinomas to the most common renal cell tumors (150 clear cell, 100 papillary, 50 chromophobe renal cell carcinomas, 18 clear cell papillary renal cell tumors, and 50 oncocytomas)." (PMID 35980471, 2022). "TFEB-associated renal cell carcinoma was not marked as an epithelial immunohistochemical marker but was marked as melanocyte markers HMB45 and melan-A." (PMID 36550835, 2022). "Indeed, cathepsin K is expressed in roughly half of TFE3-rearranged renal cell carcinomas, and is observed in virtually all TFEB-rearranged renal cell carcinomas." (PMID 34069976, 2021). "Nevertheless, it is widely accepted that both TFE3-rearranged renal cell carcinoma and TFEB-rearranged renal cell carcinoma may show a broad range of morphology, resulting in a challenging differential diagnosis." (PMID 34069976, 2021). "Thus, chromosomal translocation of TFE3 and TFEB genes are detected in renal cell carcinoma, alveolar soft part sarcoma, and perivascular epithelioid cell neoplasm." (PMID 33981707, 2021). "Moreover, in renal cell carcinoma, KHDRBS2 is reported to form fusion part with TFEB, which is associated with the aggressive behavior of renal cell carcinoma." (PMID 31032367, 2019). "While not as widely associated with all cancers, TFE3 and TFEB gene fusions are detected in subsets of renal cell carcinomas (RCC), indicating roles for these transcription factors in oncogenesis." (PMID 30520728, 2018). "TFEB has been shown to mediate resistance to mTOR inhibition in renal cell carcinoma (RCC) and to increase programmed death ligand-1 (PD-L1) expression in cancer cells, thereby promoting immune evasion." (PMID 39624081, 2024). "Besides, TFEB could elevate PD-L1 expressions to promote immune evasion resistance to mTOR inhibition in renal cell carcinoma, highlighting the significant relationships between TFEB and immunotherapy." (PMID 35773729, 2022). "Similarly, aberrant overexpression of TFEB has been reported in patients with renal cell carcinoma." (PMID 32397616, 2020). "Microphthalmia Transcription Factor (MITF)family translocation renal cell carcinoma (tRCC) is a rare RCC subtype harboring TFE3/TFEB translocations." (PMID 30591082, 2018).
renal cell carcinoma (continued). "The scope of this review will focus only on the more recently described entities and not the common ones, such as clear cell renal cell carcinoma (RCC), papillary RCC, chromophobe RCC (classic), as well as TFE3‐rearranged RCC and TFEB‐altered RCC, all of which commonly exhibit eosinophilic features." (PMID 41384711, 2026). "MiT/TFE family translocation renal cell carcinoma (tRCC) comprises Xp11 tRCC and t(6:11)RCC, which were characterized by the rearrangement of the MiT transcription factors TFE3 and TFEB, respectively." (PMID 29903018, 2018). "Here we report a metastatic TFEB-translocated, but not amplified, renal cell carcinoma in a kidney transplant patient who was consequently treated with immune therapy and tyrosine kinase inhibitors and provide a review of the current literature." (PMID 37415400, 2024). "This category of RCC includes renal oncoytoma (RO), the eosinophilic variant of chromophobe renal cell carcinoma (Chr-RCC), and some less common entities like succinate dehydrogenase (SDH)-deficient RCC, MiTF translocation RCC (especially TFEB), and epithelioid angiomyolipoma (AML)." (PMID 38892169, 2024). "Translocation renal cell carcinomas (T-RCCs) are driven by somatic translocation involving a member of microphtalmia (MiT) transcription factor family genes on chromosome X (i.e., TFE3, TFEB or MITF) with other partner genes." (PMID 36902045, 2023). "CA9 is usually negative either in TFE3 or TFEB-rearranged renal cell carcinoma whereas it is an important positive reliable marker in clear cell renal cell carcinoma." (PMID 35980471, 2022). "However, as TFE3-rearranged renal cell carcinoma, other gene fusion partners have been recently detected (COL21A1, CADM2, KHDRBS2, ACTB, EWSR1, CTLC, and NEAT1), as well as tumors harboring TFEB gene amplification despite translocation." (PMID 35980471, 2022). "CD10 is not useful in the differential diagnosis between clear cell papillary renal cell tumor and TFEB-rearranged renal cell carcinoma since both tumors are typically negative for this marker, but it helps distinguish from TFE3-rearranged renal cell carcinoma, usually positive." (PMID 35980471, 2022). "CK7 is usually negative either in TFE3 or TFEB-rearranged renal cell carcinoma whereas it is an important positive reliable marker in papillary renal cell carcinoma." (PMID 35980471, 2022). "CK7 is negative in TFE3/TFEB-rearranged renal cell carcinoma and positive in papillary renal cell carcinoma, being therefore useful in this setting." (PMID 35980471, 2022). "The occurrence of TFEB amplification in renal cell carcinoma seems to not be related to TFEB rearrangement." (PMID 34069976, 2021). "As the target DNA sequences of MiTF overlap with those of TFE3 and TFEB, it has been hypothesized that the overexpressed TFE3 fusion proteins or native TFEB in these renal cell carcinomas may have the same effect on the promoter of cathepsin K." (PMID 34069976, 2021). "MiT family translocation renal cell carcinoma (tRCC) is a sporadic RCC characterized by fusion genes involving the MiT/TFE family genes, MITF, TFEB, and TFE3 and defined as an MiT family translocation RCC in the 2016 WHO classification." (PMID 36672892, 2023). "However, in TFEB-rearranged renal cell carcinoma, CD10 and AMACR staining are not statistically correlated (p = 0.5 and p = 1 respectively)." (PMID 35980471, 2022). "Namely, whereas CA9 immunolabeling was found in 6 of 25 (24%) TFE3-rearranged renal cell carcinomas with a 5% threshold, in 2 of them (8%) and none of them (0%), respectively, referring to a 10% and 20% cutoff, all the TFEB-rearranged renal cell carcinomas were negative for such marker." (PMID 35980471, 2022). "The tight connection of TFEB and TFE3 with RCC has been reported, especially in translocation renal cell carcinoma." (PMID 33145941, 2020).
renal cell carcinoma (continued). "Microphthalmia Transcription Factor (MiTF) family translocation renal cell carcinoma (tRCC) is a subtype of RCC characterized by chromosomal translocations involving TFE3 and TFEB transcription factor genes." (PMID 30591082, 2018). "Thus, chromosomal translocations involving TFEB and TFE3 have been found in patients with clear renal cell carcinoma (RCC)." (PMID 32397616, 2020). "The tight connection of TFEB and TFE3 with clear cell renal cell carcinoma (RCC) has been reported." (PMID 29903018, 2018). "Cathepsin K is positive in TFEB-rearranged renal cell carcinoma and half of TFE3-rearranged renal cell carcinoma while it is negative in clear cell papillary renal cell tumor." (PMID 35980471, 2022). "At present, most of the studies on TFE3 and cancer focus on Xp11.2 translocation renal cell carcinoma (tRCC) but not ccRCC, a special type of RCC characterized by gene fusions involving TFE3 or TFEB." (PMID 33637706, 2021).
Alzheimer disease (49 papers, 2017 to 2026). A progressive, neurodegenerative disease characterized by loss of function and death of nerve cells in several areas of the brain leading to loss of cognitive function such as memory and language. "TFEB has been extensively implicated in various neurodegenerative diseases, such as Alzheimer's disease and PD, leading to the development of numerous agonists aimed at activating TFEB to exert neuroprotective effects." (PMID 39759118, 2025). "The dysregulation of TFEB expression and activity has been implicated in the progression of various diseases, including Parkinson's disease, Alzheimer's disease, Huntington's disease, and RagCS75Y cardiomyopathy 36-39." (PMID 38250603, 2024). "Overexpression of TFEB facilitates substrate clearance and alleviates the phenotypes associated with various diseases, such as Parkinson’s and Alzheimer’s diseases, in murine models by promoting autophagic flux." (PMID 38139347, 2023). "Ectopic overexpression of TFEB has been experimentally proven to be beneficial to induce the intracellular clearance of pathogenic factors in murine models of Parkinson’s disease, Alzheimer’s disease, atherosclerosis, and myocardial infarction." (PMID 35228523, 2022). "Notably, dysregulations of the major autophagy controller, the transcription factor EB (TFEB), have been described in Parkinson’s, Huntington’s, and Alzheimer’s diseases and are associated with elevated intracellular protein aggregation and autophagy dysfunction." (PMID 34204710, 2021). "TFEB dysregulation has been reported in several neurodegenerative diseases, mainly by reduced nuclear localization, such as in the postmortem brains of Alzheimer’s disease, Parkinson’s disease, and amyotrophic lateral sclerosis patients." (PMID 40362383, 2025). "Caudatin has also displayed neuroprotection in models of Alzheimer’s disease by activating TFEB and the autophagosome-lysosomal pathway mechanism of action, while also modulating PPARα." (PMID 40959450, 2025). "It is necessary to consider age-related lysosomal dysfunction when developing treatment strategies for TFEB-related Alzheimer’s disease." (PMID 39281281, 2024). "Apart from PD, reduced expression of TFEB in nuclear tissue fractions has been reported in different neurodegenerative diseases, including Alzheimer’s disease and Amyotrophic lateral sclerosis." (PMID 38581586, 2024). "TFEB can also affect glial cell clearance of toxic protein aggregates; astrocytic TFEB overexpression can accelerate the degradation of extracellular amyloid (beta) by neuronal autophagy in mouse models of Alzheimer's disease." (PMID 37728021, 2023). "Transcription factor EB, a master regulator of lysosomal function, regulates multiple disease genes in a specific Alzheimer’s disease astrocyte subpopulation." (PMID 34867177, 2021). "Upregulation of TFEB signaling helps clear multiple types of proteotoxic aggregates found in Alzheimer’s disease, Parkinson’s disease, Huntington’s disease, ALS and FTD." (PMID 33300868, 2020). "Previously, in CA1 pyramidal neurons of the hippocampus from Alzheimer’s disease patients, an up-regulation of the network of genes regulated by TFEB was observed, along with a decrease in autophagic flux due to an inability to clear the accumulated substrate." (PMID 32285908, 2020). "In Alzheimer’s disease patients, glia cells contain higher levels of the transcription factor TFEB, which regulates lysosomal biogenesis and autophagy, in the nucleus than neurons." (PMID 29743513, 2018). "For instance, in a mouse model of Alzheimer’s disease, protein accumulation in lysosomes resulted in lysosomal stress that led to TFEB activation, representing a line of defense that is, however, quickly overwhelmed, resulting in the progression of the disease." (PMID 40243477, 2025).